S1PR3 (sphingosine-1-phosphate receptor 3)
Description:
Receptor for the lysosphingolipid sphingosine 1-phosphate (S1P). S1P is a bioactive lysophospholipid that elicits diverse physiological effect on most types of cells and tissues. When expressed in rat HTC4 hepatoma cells, is capable of mediating S1P-induced cell proliferation and suppression of apoptosis.
Synonyms: S1P3; C9orf108; C9orf47; EDG3; EDG-3; FLJ37523; bA791O21.3; LPB3
Tractability: Small molecule: an approved drug acts on it; a structure with a bound ligand is known; a high-quality ligand is known; it belongs to a druggable protein family. Antibody: its Gene Ontology location is reachable by antibodies, with high confidence; UniProt places it where antibodies can reach, with medium confidence; UniProt predicts a signal peptide or a membrane-spanning region. PROTAC: ubiquitination databases record sites on it; its protein half-life has been measured; a small molecule that binds it is known.
Target class: EDG receptor; Family A G protein-coupled receptor; Lipid-like ligand receptor (family A GPCR); Membrane receptor; Small molecule receptor (family A GPCR)
Chemical probes: CYM 5541 (high quality), ML003, ML004, ML005, ML006
Gene: Protein-coding gene on chromosome 9 (88,990,863 to 89,005,155, forward strand). Ensembl gene ENSG00000213694.
Subcellular location: Cell membrane
Pathways (Reactome):
Signal Transduction: Extra-nuclear estrogen signaling; G alpha (i) signalling events; Lysosphingolipid and LPA receptors
Gene Ontology:
Molecular function: integrin binding; protein binding; G protein-coupled receptor activity; lipid binding; sphingosine-1-phosphate receptor activity
Biological process: negative regulation of establishment of endothelial barrier; adenylate cyclase-activating G protein-coupled receptor signaling pathway; anatomical structure morphogenesis; G protein-coupled receptor signaling pathway; inflammatory response; positive regulation of cell population proliferation; positive regulation of cytosolic calcium ion concentration; sphingosine-1-phosphate receptor signaling pathway
Cellular component: plasma membrane; cytoplasm; membrane; presynapse
Genetic constraint (gnomAD): Loss-of-function variants: 13 observed, 16.3 expected, observed/expected ratio (o/e) 0.8, 90% interval 0.52 to 1.27. The upper end of that interval is the gene's LOEUF score, 1.27, which puts it in group 5 of 6, group 1 being the genes least tolerant of losing a copy. Missense variants: 450 observed, 531.28 expected, observed/expected ratio (o/e) 0.85, 90% interval 0.78 to 0.92. Synonymous variants: 232 observed, 229.61 expected, observed/expected ratio (o/e) 1.01, 90% interval 0.91 to 1.13.
Homologues: Orthologues: macaque S1PR3 (98% identical), chimpanzee S1PR3 (92% identical), dog S1PR3 (88% identical), mouse S1pr3 (88% identical), rabbit S1PR3 (88% identical), rat S1pr3 (88% identical), pig S1PR3 (87% identical), guinea pig S1PR3 (84% identical), tropical clawed frog s1pr3 (70% identical). Paralogues in human: S1PR1 (50% identical), S1PR5 (42% identical), S1PR2 (40% identical), S1PR4 (38% identical), LPAR1 (30% identical), LPAR3 (30% identical), LPAR2 (28% identical), CNR1 (24% identical), GPR12 (22% identical), GPR6 (22% identical), MC5R (21% identical), GPR3 (21% identical), and 6 more.
Diseases named in the same sentence as S1PR3 in open-access papers:
S1PR3 is named in the same sentence as 139 diseases in open-access papers, as found by Europe PMC text mining. Sharing a sentence is not in itself a finding about the gene and the disease. The quoted sentences say what the papers report.
breast carcinoma (30 papers, 2009 to 2025). "The upregulation of astrocytic S1PR3 was linked to high permeability of brain metastases from breast cancer, suggesting contrary pathophysiological effects of S1PR3 to those of S1PR1." (PMID 34959306, 2021). "S1P binding to S1PR3 is associated with SphK1 translocation of SphK1 to the plasma membrane to promote tumorigenesis in ER+ breast cancer." (PMID 28415564, 2017). "SPHK1 and S1PR3 expression in human breast cancer tissue is associated with reduced time to recurrence and cumulative disease-specific survival." (PMID 27129165, 2016). "Two receptors, S1PR1 and S1PR3, are associated with breast cancer progression." (PMID 39767749, 2024). "S1PR1 and S1PR3 have been linked to breast cancer progression." (PMID 39767749, 2024). "In addition to ERK, SPHK1/S1P/S1PR3 axis has been implicated in potentiating the progression of breast cancer through upregulations of C-reactive protein (CRP) and MMP9." (PMID 34820423, 2021). "S1P subsequently binds to S1PR3 to cause breast cancer growth." (PMID 33758708, 2021). "The binding of S1P with S1PR3 promotes the phosphorylation of ERK1/2 and encourages its localization via an S1P3/ p21-activated protein kinase 1(PAK1)-dependent pathway in breast cancer cell models." (PMID 38419070, 2024). "Specifically in triple-negative breast cancer cell lines, S1P/S1PR3/Notch signaling was found to promote metastasis, making S1PR3 a therapeutic target for breast cancer treatment." (PMID 35565311, 2022). "In support of these findings, breast cancer patient-derived CSCs were found to contain positive S1PR3/ALDH1 or SPHK1/ALDH1 cells." (PMID 35565311, 2022). "A study reinforced the importance of S1PR1 and S1PR3 in breast cancer growth and adhesion by silencing the genes for these two receptors, resulting in a statistically reduced growth in the breast cancer tumors." (PMID 33758708, 2021). "Most of the S1PR3’s breast cancer effects are due to the constant activation of ERK1/2 and AKT/PI3K pathways." (PMID 33920887, 2021). "S1PR3 is overexpressed in breast cancer cell lines, promoting cancer progression and reducing the overall survival rate in breast cancer patients." (PMID 33920887, 2021). "We have previously reported membrane and cytosolic localization of S1PR3 in MCF-7 breast cancer cells." (PMID 29385066, 2018). "Accordingly, it was suggested that SphK1 can regulate cell responsiveness to S1P by increasing S1PR3 expression levels, thus producing a positive amplification loop of S1PR3-mediated invasive signaling in breast cancer cells." (PMID 29385066, 2018). "Our findings suggest S1PR3 is a determinant of phthalate-driven breast cancer metastasis and a possible therapeutic target for regulating BCSC populations." (PMID 27129165, 2016). "SPHK1 or S1PR3 knockdown in breast cancer cells effectively reduced tumor growth and lung metastasis in vivo." (PMID 27129165, 2016). "Our results implicate S1PR3 as a potentially valuable therapeutic target for regulating BCSCs in breast cancer patients." (PMID 27129165, 2016). "S1PR3 is the most highly expressed S1PR in human breast cancer cells." (PMID 34820423, 2021). "Moreover, studies have indicated that SPHK1/S1P/S1PR3 signaling axis promotes tumorigenicity and metastasis of breast cancer by activating p38 mitogen-activated protein kinase (MAPK)/Notch signaling." (PMID 34820423, 2021). "Among S1PRs, S1PR3 is known to be most highly expressed in breast cancer cells." (PMID 34298877, 2021). "Upregulation of S1PR3 was recently detected in analysis of metastatic breast cancer lines." (PMID 29385066, 2018). "In estrogen receptor positive (ER+) tumors high S1PR1 and S1PR3 were reported to be causally associated with tamoxifen resistance and poor prognosis, and in vitro, in ER+ MCF-7 breast cancer cells, the SphK1/S1PR3 loop promoted breast cancer progression and migration." (PMID 28415564, 2017).
breast carcinoma (continued). "In breast cancer cell lines, however, the use of tamoxifen and medroxyprogesterone result in the downregulation of S1PR3 and stimulation of S1PR2 with activation of autophagy of the breast cancer cells towards death, again demonstrating the detrimental role of S1P pathway activation in cancer." (PMID 29147072, 2017). "These mice had a prolonged survival rate, suggesting that S1PR3 could be a potential prognostic biomarker in breast cancer." (PMID 27129165, 2016). "Knockdown of SPHK1 or S1PR3 reduced breast cancer cell tumorigenicity." (PMID 27129165, 2016). "Moreover, S1PR3 was important for insulin-mediated mitogenic action in breast cancer cells." (PMID 29385066, 2018). "Many have also attempted to investigate the involvement of S1PRs in the signaling cascades of SPHK1/S1P axis in human cancers, whereby substantial evidence has highlighted the interactions between SPHK1/S1P axis with S1PR1, S1PR3, and S1PR4 in breast cancer." (PMID 34820423, 2021). "S1P enhances invasion and migration of breast cancer cells both in vitro and in vivo by inducing the expression of matrix metalloproteinase-9 (MMP-9) in the S1P/S1PR3/Gαq axis." (PMID 35201458, 2021). "The S1PR3-driven oncogenic effects are mainly ascribed to the activation of ERK1/2 signaling pathways, which have been known as key regulatory mechanisms in the cell cycle progression, survival, and proliferation of breast cancer cells." (PMID 34820423, 2021). "It has been demonstrated that coupling of S1P to S1PR3 can induce CRP expression via CCAAT/enhancer-binding protein β (C/EBPβ), activate Rac1/Nox-4/ROS/ERK pathways, and upregulate MMP9 activity, contributing to the aggressiveness and invasion of breast cancer." (PMID 34820423, 2021).
atherosclerosis (13 papers, 2012 to 2025). A disease characterized by the build-up of fatty material and calcium deposition in the arterial wall resulting in partial or complete occlusion of the arterial lumen. "The in vivo consequences of S1PR3 deficiency for atherosclerosis are in line with its positive role in cholesterol efflux." (PMID 36077004, 2022). "S1PR3 also plays a protective role in atherosclerosis by promoting endothelial cell migration and inhibiting the apoptosis of macrophages through PI3K/AKT and STAT3/Survivin signals, respectively." (PMID 40092491, 2025). "To explore the significance of these findings for atherosclerosis, we performed a new series of experiments to compare atherosclerotic lesion development in ApoE−/−/S1PR3−/− mice versus ApoE−/−/S1PR3+/+ mice on a Western diet for 12 weeks with and without DOP." (PMID 36077004, 2022). "Although S1PR3 is recognized to play a positive role in neovascularization, the effect of S1PR3 on endothelial barrier integrity and atherosclerosis remains elusive." (PMID 34977175, 2021). "In vivo and in vitro experiments indicate that S1P mediates S1PR3 to recruit monocytes/macrophages and change smooth muscle cells to protect them from atherosclerosis." (PMID 30627532, 2018). "In addition, genetic deletion of either S1pr2 or S1pr3 diminished atherosclerosis associated with suppression of macrophage infiltration in a murine model, indicating that S1PR2 and S1PR3 facilitate atherosclerosis." (PMID 31797978, 2019). "In mouse models of atherosclerosis, genetic knockout (KO) studies showed that S1PR2 and S1PR3 facilitate atherosclerosis, whereas pharmacological stimulation of S1PR1diminishes atherosclerosis." (PMID 31797978, 2019). "This was dependent on S1P signaling through S1PR3 and resulted in dramatically enhanced atherosclerosis in ApoE−/−/S1PR3−/− mice, where DOP treatment had no additional effect." (PMID 36077004, 2022). "Additionally, the finding that FTY20 inhibited S1PR3 and S1PR4 in macrophage foam cells was similar to previous reports that FTY20 could suppress S1PR1 and S1PR3 to decrease inflammatory factors and alleviate atherosclerosis." (PMID 30627532, 2018).
Sepsis (13 papers, 2012 to 2025). Sepsis is defined as life-threatening organ dysfunction caused by a dysregulated host response to infection. "The two S1PR3 promoter SNPs reduce S1PR3 promoter activity, reduce plasma S1PR3 levels in sepsis and ARDS, and are associated with decreased risk for sepsis-associated ARDS." (PMID 38345908, 2024). "Several studies already indicated that S1P-S1PR3 signaling drove bacterial killing, S1PR3 was associated with preferable sepsis outcomes." (PMID 33549110, 2021). "To achieve this aim, we examined whole blood gene expression in two standalone cohorts from Gene Expression Omnibus (GEO) and identified a gene signature of 18 genes significantly associated both with S1PR3 and sepsis survival." (PMID 33549110, 2021). "However, S1PR3 causes increased mortality in sepsis patients by delaying the maturation of phagosomes in macrophages." (PMID 37746079, 2023). "S1PR3 is found in most organ tissues, and current research focuses on cardiovascular issues, sepsis, cardiac conduction, stroke, and cancer metabolism." (PMID 37746079, 2023). "Since ATP plays an essential role as an extracellular signaling molecule in the development of sepsis and septic organ failure, we focused on the mechanism of S1PR3 in ATP-induced NLRP3 inflammasome activation in our research." (PMID 36798132, 2023). "S1PR1 and S1PR3 play a diverse role and belongs to different signaling pathways in sepsis progression." (PMID 33549110, 2021). "To find the connection between S1PR3 pathways and genes that affect sepsis survival, we intersected the S1PR3-related genes and sepsis survival-related genes and identified 18 overlapping genes." (PMID 33549110, 2021). "Among all these five S1PRs, S1PR3 regulates many parts of the vascular barrier and inflammatory responses in several pathological disorders related to the sepsis mediated pro-inflammatory response." (PMID 33549110, 2021). "In general, S1PR1 and S1PR3 gene signature have diverse molecular mechanisms in the pathology of sepsis, so we decided to publish them separately." (PMID 33549110, 2021). "S1PR3 is also noted to be significantly upregulated in acute respiratory distress syndrome, a pulmonary consequence of sepsis, suggesting a key role in inflammation regulation." (PMID 33549110, 2021). "In this study, we chose two gene expression datasets from the GEO database which contain whole blood samples from sepsis patients with clinical outcome information to identify an S1PR3 gene signature." (PMID 33549110, 2021). "Finding S1PR3 gene signatures in sepsis will reveal several biological or clinical features of the pathogenesis and progression of sepsis." (PMID 33549110, 2021). "This strongly indicates that the S3MS signature builds a bridge between S1PR3 and sepsis survival-related genes." (PMID 33549110, 2021). "S1PR3 is an attractive biomarker candidate due to its involvement in several signaling pathways and gene co-expression related to sepsis." (PMID 33549110, 2021). "A previous study in models of ARDS showed that S1PR-3 promotes pulmonary inflammation in the late phase of sepsis via PAR1-S1PR-3 cross talk, propagating the dissemination of IL-1 and tissue factor to the lungs." (PMID 31483837, 2019). "S1PR3’s contributions to the inflammatory cascade, however, are more complex, as inhibition of S1PR3 suppresses NLPR3 inflammasome activation in sepsis models and reduces NF-kB-driven cytokine production, suggesting a potential role in limiting excessive immune activation." (PMID 41511294, 2025). "Next, we examined the role of S1PR3 in sepsis with the S1PR3 antagonist, TY52156." (PMID 36798132, 2023). "We desire to find those genes regulated by S1PR3 which may reflect the clinical outcome of sepsis patients." (PMID 33549110, 2021). "However, we specifically derived the 18-gene signature based on the S1PR3 processes which are strongly related to the development of sepsis." (PMID 33549110, 2021). "S1PR3′s function in sepsis has been studied by multiple groups." (PMID 33549110, 2021).
Sepsis (continued). "Enhancing endogenous S1PR3 activity using a peptide agonist potentiated ROS production and bactericidal function in macrophages, resulting in decreased bacterial burden, less tissue injury, and improved survival rates in multiple models of sepsis." (PMID 30944018, 2019). "Therefore, our gene signature from S1PR3 has the potential to predict clinical outcomes in sepsis." (PMID 33549110, 2021). "Therefore, S1PR3 is essential for survival in sepsis, and S1PR3-regulated cell signaling pathways in sepsis may offer a novel role in therapy." (PMID 33549110, 2021). "In addition, previous studies revealed that S1P and its receptors, especially S1PR-3, are involved in the vascular integrity disruption in ALI, and increased S1PR-3 concentrations have been reported to be associated with mortality in intensive care unit patients with sepsis or ALI." (PMID 32185202, 2020).
liver fibrosis (12 papers, 2014 to 2022). "Finally, we analyzed the effects of S1PR2 and S1PR3 antagonists on the underlying liver fibrosis process." (PMID 26324256, 2015). "S1PR3, a critical factor in fibrosis, is significantly overexpressed in hepatic fibrosis; hence, the silencing of its gene inhibits hepatic fibrosis." (PMID 35200103, 2022). "MTT, Transwell, qRT-PCR, Western blot, and flow cytometry analyses further elucidated the mechanisms of the miR-495-3p/S1PR3 axis in hepatic fibrosis regulation." (PMID 35200103, 2022). "Upregulation of S1PR-3 was reported in lung adenocarcinoma cells, astrocytes, and a mouse model of cholestasis-induced liver fibrosis." (PMID 32185202, 2020). "S1PR3 expression was elevated in cholestasis-induced hepatic fibrosis, and S1PR3 inhibition led to reduced fibrosis in this model." (PMID 28322247, 2017). "HuR promotes the migration of BMSCs by increasing S1PR3 mRNA stability and expression, which may affect liver fibrosis." (PMID 36375472, 2022). "Hence, we performed functional experiments to unveil the miR-495-3p/S1PR3 regulatory axis in hepatic fibrosis." (PMID 35200103, 2022). "Therefore, this study was aimed at investigating the role of the NORAD/miR-495-3p-S1PR3 axis in the activation of HSCs, and revealing its mechanism, thereby providing a new theoretical basis for the treatment of hepatic fibrosis." (PMID 35200103, 2022). "NORAD inhibition could suppress HSC activation by modulating the miR-495-3p/S1PR3 axis, providing new insights for hepatic fibrosis treatment." (PMID 35200103, 2022). "S1PR3 is involved in bone marrow derived mesenchymal stem cells migration during liver fibrosis." (PMID 31546702, 2019). "It has been demonstrated that the S1PR3 is upregulated during liver fibrosis." (PMID 29510489, 2018). "However, several studies have indicated that the S1PR3 is the critical receptor subtype involved in liver fibrosis." (PMID 29510489, 2018). "Therefore, in this study, we hypothesized that NORAD might play an important role in hepatic fibrosis by regulating the miR-495-3p/S1PR3 axis." (PMID 35200103, 2022).